PHOX2B (paired like homeobox 2B)
Description:
Involved in the development of several major noradrenergic neuron populations, including the locus coeruleus. Transcription factor which could determine a neurotransmitter phenotype in vertebrates. Enhances second-messenger-mediated activation of the dopamine beta-hydrolase and c-fos promoters, and of several enhancers including cAMP-response element and serum-response element.
Synonyms: NBPhox; PMX2B; CCHS; NBLST2
Tractability: No criterion of Open Targets' tractability assessment is met for any kind of drug.
Gene: Protein-coding gene on chromosome 4 (41,744,082 to 41,748,725, reverse strand). Ensembl gene ENSG00000109132.
Subcellular location: Nucleus
Subcellular location (Human Protein Atlas): Nucleoplasm
Gene Ontology:
Molecular function: DNA-binding transcription activator activity, RNA polymerase II-specific; RNA polymerase II cis-regulatory region sequence-specific DNA binding; RNA polymerase II transcription regulatory region sequence-specific DNA binding; sequence-specific double-stranded DNA binding; DNA-binding transcription factor activity, RNA polymerase II-specific; DNA binding
Biological process: autonomic nervous system development; brainstem development; enteric nervous system development; positive regulation of transcription by RNA polymerase II; regulation of transcription by RNA polymerase II; cell differentiation in hindbrain; cellular response to BMP stimulus; dopaminergic neuron differentiation; efferent axon development in a lateral line nerve; glial cell differentiation; hindbrain tangential cell migration; inner ear development; medullary reticular formation development; neural crest cell migration involved in autonomic nervous system development; neuron development; neuron migration; noradrenergic neuron development; noradrenergic neuron differentiation; parasympathetic nervous system development; positive regulation of cold-induced thermogenesis; positive regulation of G2/M transition of mitotic cell cycle; regulation of gene expression; regulation of respiratory gaseous exchange by nervous system process; respiratory system development; retrotrapezoid nucleus neuron differentiation; and 3 more
Cellular component: chromatin; nucleoplasm; nucleus
Genetic constraint (gnomAD): Loss-of-function variants: 1 observed, 13.58 expected, observed/expected ratio (o/e) 0.0736, 90% interval 0.025 to 0.35. The upper end of that interval is the gene's LOEUF score, 0.35, which puts it in group 1 of 6, group 1 being the genes least tolerant of losing a copy. Missense variants: 309 observed, 377.69 expected, observed/expected ratio (o/e) 0.82, 90% interval 0.75 to 0.9. Synonymous variants: 204 observed, 168.75 expected, observed/expected ratio (o/e) 1.21, 90% interval 1.08 to 1.36.
Gene-disease validity (ClinGen):
ClinGen rates the evidence that PHOX2B causes each of these diseases.
central hypoventilation syndrome, congenital, 1, with or without Hirschsprung disease (autosomal dominant): Definitive. A rare disease due to a severely impaired central autonomic control of breathing and dysfunction of the autonomous nervous system.
Haddad syndrome (autosomal dominant): Definitive. Haddad syndrome is a rare congenital disorder in which congenital central hypoventilation syndrome (CCHS), or Ondine syndrome, occurs concurrently with Hirschsprung disease.
Cancer hallmarks: suppression of growth (promotes); invasion and metastasis (suppresses)
Homologues: Orthologues: chimpanzee PHOX2B (100% identical), macaque PHOX2B (100% identical), mouse Phox2b (100% identical), rat Phox2b (100% identical), pig PHOX2B (99% identical), guinea pig PHOX2B (82% identical), tropical clawed frog phox2b (82% identical), zebrafish phox2bb (80% identical). Paralogues in human: PHOX2A (54% identical), ARX (28% identical), DRGX (25% identical), RAX (24% identical), UNCX (24% identical), ALX4 (24% identical), ALX3 (23% identical), PAX7 (23% identical), PRRX1 (23% identical), ALX1 (22% identical), PITX2 (22% identical), PRRX2 (22% identical), and 38 more.
Diseases named in the same sentence as PHOX2B in open-access papers:
PHOX2B is named in the same sentence as 113 diseases in open-access papers, as found by Europe PMC text mining. Sharing a sentence is not in itself a finding about the gene and the disease. The quoted sentences say what the papers report.
neuroblastoma (144 papers, 2009 to 2026). Neuroblastoma (NB) is the most common solid, extracranial childhood tumor. "In fact, it was the first gene for which germline mutations were discovered in neuroblastoma and low expression of PHOX2B is associated with a higher tumor stage, poor outcome and poor survival." (PMID 40104501, 2025). "PHOX2B is a master regulator of neurogenesis and a key player in the development of neuroblastoma, whose expression level is tightly associated with the growth rates of neuroblastoma cell lines." (PMID 40930101, 2025). "The vast majority of neuroblastomas exhibit mutations in PHOX2B, which is a neural crest gene involved in the formation of the peripheral nervous system." (PMID 38673496, 2024). "In patients with neuroblastoma, different heterozygous missense and nonsense germline mutations of PHOX2B have been detected." (PMID 38666930, 2024). "Detecting the missense mutation c.422G > A (p.Arg141Gln) in the PHOX2B gene implies its potential pathogenic role within this neuroblastoma family." (PMID 38420445, 2024). "Loss-of-function mutations in PHOX2B have been demonstrated to hinder the differentiation of neuroblastoma by impeding the maturation of early sympathetic neurons." (PMID 38673496, 2024). "Because the TATA/TATA genotype causes low LMO1 expression and LMO1 is required for the adrenergic CRC to form, we predict that the TATA/TATA genotype would protect against neuroblastoma in patients with germline activating mutations of PHOX2B." (PMID 37183825, 2023). "IGF2BP1-driven malignancies are reminiscent to human high-risk neuroblastoma, including 2p/17q-syntenic chromosomal gains and upregulation of Mycn, Birc5, as well as key neuroblastoma circuit factors like Phox2b." (PMID 37246217, 2023). "This was associated with elevated expression of neuroblastoma (e.g. Phox2b), sympatho-adrenal (e.g. Th), neural (e.g. Gap43), neural stem cell (e.g. Msi1) and neural crest cell markers (e.g. Tfap2b)." (PMID 37246217, 2023). "Germline mutations of anaplastic lymphoma kinase (ALK) and paired-like homeobox 2B (PHOX2B) genes are pivotal predisposition factors in hereditary neuroblastoma." (PMID 35454815, 2022). "Congenital anomalies of the autonomic nervous system in association with neuroblastoma are commonly associated with germline mutations in PHOX2B." (PMID 36140661, 2022). "The first neuroblastoma predisposition gene identified was paired-like homeobox 2B (PHOX2B), found in a familial case of neuroblastoma." (PMID 34769149, 2021). "Germline mutations of PHOX2B occur in <10% of hereditary cases of neuroblastoma, whereas somatic PHOX2B mutations are rarely found in sporadic cases." (PMID 34796286, 2021). "PHOX2B encodes neuroblastoma Phox (paired-like homeobox 2B) protein, which plays a role in neuron development and involves in the determination of the neurotransmitter phenotype." (PMID 33468206, 2021). "As one of the major disease-causing genes in central hypoventilation syndrome, germline mutations in PHOX2B were first found in neuroblastoma patients." (PMID 33585230, 2020). "It is related to mutations in the paired-like homeobox 2B (PHOX2B) gene and is associated with the Hirschsprung disease, neuroblastoma, and autonomic nerve dysfunctions." (PMID 32660452, 2020). "Among the frequently mutated genes, activating mutations in the ALK kinase and loss-of-function mutations in the paired-like homeobox 2b (PHOX2B) transcription factor account for ~80% of hereditary neuroblastomas." (PMID 31480495, 2019). "When BM samples are evaluated by a set of five markers (CHRNA3, DDC, GAP43, PHOX2B, and TH), unfavorable outcome in localized neuroblastoma patients is associated with the detection of more than one positive-marker." (PMID 31214500, 2019). "PHOX2B mutations were observed in congenital central hypoventilation syndrome, neuroblastoma and Hirschsprung disease." (PMID 31652452, 2019).
neuroblastoma (continued). "Stratification analysis of the association between PHOX2B rs28647582 T>C polymorphism and neuroblastoma risk." (PMID 30799307, 2019). "Heterozygous germline mutations as well as somatic mutations of PHOX2B are present in a subset of neuroblastomas." (PMID 30760980, 2019). "Another study explained that certain PHOX2B variants are associated with neuroblastoma pathogenesis because of their inability to bind to key interacting proteins such as HPCAL1." (PMID 30889216, 2019). "MRD detection in BM samples evaluated by a set of five markers (CHRNA3, DDC, GAP43, PHOX2B, and TH) was associated with poor outcome in patients aged over 1 year with stage 4 neuroblastoma." (PMID 31214500, 2019). "Familial cases of both HSCR and neuroblastoma appear to be functionally linked to PHOX2B, which plays a key role in the development of neural crest derivatives." (PMID 30799307, 2019). "Of note, not all families with neuroblastoma had a PHOX2B mutation, suggesting that other predisposition genes were yet to be discovered, and we now know that about six to ten percent of familial neuroblastoma cases will have a mutation in PHOX2B." (PMID 30200332, 2018). "Both Trochet and Mosse took blood from families with familial neuroblastoma and sequenced the PHOX2B gene discovering mutations in PHOX2B that passed from parents to their children." (PMID 30200332, 2018). "Missense mutations in PHOX2B, located on chromosome 4p, were the first germline mutations identified to be associated with neuroblastoma predisposition." (PMID 30285664, 2018). "These insights culminated in the recognition that mutations in PHOX2B predispose children to familial neuroblastoma." (PMID 30200332, 2018). "It has been noted that central hypoventilation syndrome (CHS) resulting from PHOX2B mutations is associated with tumors of neural crest origin (neuroblastoma, ganglioneuroblastoma, and ganglioneuroma) in approximately 6% of cases." (PMID 30584530, 2018). "For instance, anaplastic lymphoma kinase (ALK) and PHOX2B gene variants are among the predisposing factors to familial neuroblastoma." (PMID 30285664, 2018). "The pathogenic role of the PHOX2B gene in neuroblastoma is indicated by heterozygous mutations in neuroblastoma patients and by gene overexpression in both neuroblastoma cell lines and tumor samples." (PMID 29069774, 2017). "Germline mutations of PHOX2B predispose to hereditary neuroblastoma and have also been observed in sporadic cases, but remain a rare cause of neuroblastoma." (PMID 26771642, 2016). "PHOX2B was the first gene for which germline mutations - such as heterozygous missense and nonsense mutations - were found in patients with neuroblastoma." (PMID 26840262, 2016). "Subtyping neuroblastoma tumors indicated that low expression of PHOX2B is associated with higher tumor stage, poor outcome and poor survival." (PMID 26840262, 2016). "Mutations in PHOX2B gene and anaplastic lymphoma kinase (Alk) have been identified in both familial and sporadic cases of the neuroblastoma." (PMID 25928806, 2014). "An alteration in Phox2b function in the zebrafish, by either MO knockdown or overexpression of certain neuroblastoma-associated variants, led to a block in the differentiation of sympathetic progenitor cells." (PMID 23754957, 2013). "Heterozygous germline mutations and deletions in PHOX2B, a key regulator of autonomic neuron development, predispose to neuroblastoma, a tumor of the peripheral sympathetic nervous system." (PMID 23754957, 2013). "In this study we sought to analyze the effects of aberrant PHOX2B expression on sympathetic neuron development for each of the major classes of neuroblastoma-associated mutants." (PMID 23754957, 2013). "This indicates a central role for aberrant PHOX2B regulation of immature sympathetic neurons in neuroblastoma predisposition." (PMID 23754957, 2013). "We next examined the effects of three distinct neuroblastoma-associated PHOX2B mutations on PSNS development." (PMID 23754957, 2013).
neuroblastoma (continued). "In agreement with our data, another group reported resistance to differentiation with RA in human neuroblastoma cells engineered to express the 676delG variant (in the presence of endogenous PHOX2B)." (PMID 23754957, 2013). "We also observe increased levels of methylation in other cancer related genes e.g. ALX3 and PHOX2B both implicated in neuroblastoma." (PMID 22174824, 2011). "The genes exhibiting methylation values above normal samples include the oncogene PHOX2B, the neuroblastoma associated gene ALX3, the commonly methylated PCDHα gene cluster, POU4F2, REXO1L1, BAPX1, and the potassium-channel KCNJ8." (PMID 22174824, 2011). "Additionally, PHOX2B plays a role in the genetic landscape of neuroblastoma, with mutations detected in both familial and sporadic forms of this rare cancer." (PMID 41578938, 2026). "The PHOX2B (paired like homeobox 2B) gene is essential in the development of the autonomic nervous system, promoting neural crest cell differentiation, and PHOX2B mutations are associated with peripheral neuroblastic tumors such as neuroblastoma." (PMID 40104501, 2025). "Additionally, in the last decade PHOX2B has moved to the main genetic landscape of neuroblastoma, becoming a reliable diagnostic marker in tissue and cytology specimens, and a specific and sensitive biomarker for minimal residual disease in neuroblastoma." (PMID 38666930, 2024). "Moreover, we can anticipate how the TATA/TATA genotype would influence the penetrance of neuroblastoma in children who also have germline predisposition due to activating mutations of PHOX2B or ALK." (PMID 37183825, 2023). "The most frequently harbored alterations of specific genes in neuroblastoma include heritable mutations in the ALK and PHOX2B observed in familial neuroblastoma, chromatin remodeling genes like ATRX, ARID1A and ARID1B and other important genes like PTPN11, MYCN, and NRAS." (PMID 37274289, 2023). "Additionally, germline loss-of-function mutations of the paired-like homeobox 2B (PHOX2B) gene have been found in familial neuroblastoma as well as in approximately 4% of spontaneous neuroblastomas." (PMID 35362827, 2022). "In 2004, PHOX2B (paired-like homeobox 2b) was the first to be identified as a neuroblastoma predisposition gene, and in 2008, the ALK (anaplastic lymphoma kinase) gene was reported as the major cause of hereditary neuroblastoma, and shown to also be frequently mutated in sporadic neuroblastoma." (PMID 36140661, 2022). "PHOX2B polyalanin expansion and frameshift mutations have been linked to CNS disease (i.e., congenital central hypoventilation syndrome) with neural crest‐derived tumors (neuroblastoma) and neural crest migration defects (Hirschsprung disease)." (PMID 35763016, 2022). "Furthermore, the transcription factor PHOX2B is an immunohistochemical marker for neuroblastoma and a predisposing gene to hereditary neuroblastic tumors." (PMID 35197367, 2022). "PHOX2B encodes a transcription factor essential for autonomic nervous system development, where it functions in sympathoadrenal specification, supporting the idea that neuroblastoma arises due to pathological development in this neural-crest-derived lineage." (PMID 34769149, 2021). "Analysis of the action of neuroblastoma PHOX2b variants in developing sympathetic neurons demonstrated their stimulatory effect on neuroblast proliferation combined with dedifferentiation indicating routes to malignancy modulated by PHOX2b in combination with HAND2." (PMID 34757495, 2021). "The first predisposition gene identified in neuroblastoma was PHOX2B, a gene encoding a paired homeodomain transcription factor that promotes cell cycle exit and neuronal differentiation that plays a critical role in the development of neural crest-derived autonomic neurons." (PMID 34796286, 2021). "Mutations in the PHOX2B gene might also entail a higher risk for the development of tumors originating in the neural crest (neuroblastoma, ganglioneuroma, ganglioneuroblastoma)." (PMID 34949014, 2021).